KCNT1 (potassium sodium-activated channel subfamily T member 1)
Diseases named in the same sentence as KCNT1 in open-access papers (continued):
Sharing a sentence is not in itself a finding about the gene and the disease.
autosomal dominant nocturnal frontal lobe epilepsy (15 papers, 2014 to 2025). A seizure disorder characterized by intermittent dystonia and/or choreoathetoid movements that occur during sleep. "Gain-of-function variants in KCNT1 have also been found in patients with other epileptic syndromes, including autosomal dominant nocturnal frontal lobe epilepsy, Ohtahara syndrome, and Lennox-Gastaut syndrome." (PMID 36173683, 2022). "In 2012 we identified heterozygous KCNT1 missense mutations in families and individuals with autosomal dominant nocturnal frontal lobe epilepsy (ADNFLE), now known as autosomal dominant sleep-related hypermotor epilepsy (ADSHE)." (PMID 36499459, 2022). "KCNT1 mutations were discovered in autosomal dominant nocturnal frontal lobe epilepsy (ADNFLE) and in malignant migrating focal seizures of infancy." (PMID 30477182, 2018). "Dominant mutations in KCNT1 were recently reported to cause autosomal dominant nocturnal frontal lobe epilepsy (ADNFLE), malignant migrating partial seizures of infancy (MMPSI) and infantile spasms." (PMID 24463883, 2014). "Autosomal dominant nocturnal frontal lobe epilepsy (ADNFLE) is caused by mutations in the CHRNA4, CHRNA2, CHRNB2, or KCNT1(Slack) genes." (PMID 25784856, 2015). "Autosomal dominant nocturnal frontal lobe epilepsy (ADNFLE) is a familial partial epilepsy linked to mutations in the α2, α4, and β2 nicotinic acetylcholine (ACh) receptor (nAChR) subunits, and the Na+-gated K+ channel, KCNT1." (PMID 27336596, 2016).
focal epilepsy (8 papers, 2016 to 2025). A seizure caused by a localized disorder. "Gain-of-function KCNT1 pathogenic variants cause a spectrum of severe focal epilepsies with onset in early infancy." (PMID 29196579, 2018). "Altogether, these results suggest that, based on the proband's genetic and functional characteristics, the antidepressant drug fluoxetine may be repurposed for the treatment of focal epilepsy caused by gain-of-function variants in KCNT1." (PMID 38644974, 2024). "In addition, a GOF mutation in KCNT1, encoding for a sodium-activated potassium channel KNa1.1, has been reported in patients with focal epilepsy." (PMID 35359577, 2022). "The involvement of KCNT1 in these distinct disorders suggests that KCNT1 mutations may cause a spectrum of focal epilepsies." (PMID 27064559, 2016). "In summary, our findings broadened the mutation database in relation to KCNT1 and implicated the sodium-gated potassium channel complex in ADNFLE, more broadly, in the pathogenesis of focal epilepsies." (PMID 34567798, 2021). "This individual had a clinical diagnosis of focal epilepsy with a genetic diagnosis of a likely pathogenic variant in KCNT1 that matches their phenotype and no clinical features indicative of FAME or PME." (PMID 41268177, 2025).
focal seizures (8 papers, 2018 to 2025). "In this report, we describe a 17 years-old male patient from a KCNT1 mutation family who exhibited complex abnormal behaviors during sleep, which have been confirmed as epileptic seizures combined with NREM parasomnias through video-electroencephalogram (vEEG) and video-polysomnography (vPSG)." (PMID 38073640, 2023).
Intellectual disability (8 papers, 2014 to 2025). "Patients displaying KCNT1 mutations have a very high occurrence of severe mental and intellectual disability." (PMID 27064559, 2016). "Four missense mutations (p.Arg398Gln, p.Tyr796His, p.Met896Ile, and p.Arg928Cys) in KCNT1 gene were reported to be associated with ADNFLE cases showing comorbidities of intellectual disability and psychiatric features." (PMID 27064559, 2016). "As a notable example, the occurrence of intellectual disability and other psychiatric illnesses appear to be greatly increased in those families with a KCNT1 mutation." (PMID 25120433, 2014). "This table summarizes the key findings of studies on Slo2/KCNT1/KCNT2 channels in intellectual disability, with GRADE ratings and rationale highlighting limitations, sample size, model relevance, and translational applicability." (PMID 41189825, 2025). "Developmental delay, cognitive impairment, and intellectual disabilities may also be present in younger patients; however, the symptoms and incidence were milder and lower, respectively, than those of KCNT1 mutant carriers." (PMID 38966089, 2024). "The original assumption that patients with SHE do not report gross psychological and cognitive deficits was questioned by some studies, revealing intellectual disability and psychiatric problems in patients with SHE carrying nAChR subunits and KCNT1 gene mutations." (PMID 36615172, 2023). "The search combined relevant keywords and MeSH related to Slo2 channels, KCNT1/KCNT2, sodium-activated potassium channels, intellectual disability, and neurological disorders." (PMID 41189825, 2025).
developmental and epileptic encephalopathy (6 papers, 2022 to 2025). An epilepsy associated with developmental impairment that may be due to either the underlying etiology or the superimposed epileptic activity, or both. "More than 20 recurrent missense gain-of-function (GOF) mutations have been identified in the sodium-activated potassium (KNa) channel gene KCNT1 in patients with severe developmental and epileptic encephalopathies (DEEs), most of which are resistant to current therapies." (PMID 39392867, 2024).
epilepsy of infancy with migrating focal seizures (6 papers, 2016 to 2025). This syndrome is characterized by onset of refractory focal seizures in the first year of life, with associated severe encephalopathy. "Gain-of-function mutations in KCNT1, the gene encoding Slack (KNa1.1) channels, result in epilepsy of infancy with migrating focal seizures (EIMFS) and several other forms of epilepsy associated with severe intellectual disability." (PMID 32081855, 2020).
malignant migrating partial seizures of infancy (6 papers, 2013 to 2025). A very rare severe form of epilepsy with poor prognosis that usually begins within a few weeks of birth. "Two de novo heterozygous KCNT1 mutations were identified in unrelated malignant migrating partial seizures of infancy (MMPSI) patients." (PMID 41189825, 2025). "KCNT1 mutations lead to migrating partial seizures of infancy (MMPSI), a severe and pharmacoresistant early onset epileptic encephalopathy." (PMID 31940887, 2020). "Moreover, a gain-of-function mutation in the Kcnt1 gene, a gene whose function is closely related to that of Kcnt2, has been recently associated with a childhood epileptic syndrome called malignant migrating partial seizures in infancy (MMPSI)." (PMID 24068938, 2013).
developmental delay (5 papers, 2016 to 2025). "Indeed, 2 of the 5 KCNT1-positive patients identified by the diagnostic panel from a larger cohort of 800 patients with EOEE/developmental delay had an NFLE-like presentation." (PMID 29196579, 2018). "We identified pathogenic variants in KCNT1 in 12 patients, 5 through direct Sanger sequencing, 2 from whole-exome sequencing, and 5 from the Great Ormond Street Hospital diagnostic panel (5 of 800 tested patients with EOEE/developmental delay)." (PMID 29196579, 2018).
epilepsy syndrome (5 papers, 2020 to 2024). A syndrome that has a characteristic cluster of clinical features and/or lectroencephalographic (EEG) findings that reflect underlying epileptic activity. "Gain-of-function variants in KCNT1 are associated with a spectrum of epilepsy syndromes, and mice carrying those variants exhibit a robust phenotype similar to that observed in patients." (PMID 39595574, 2024). "Mutations of the Na+-activated K+ channel Slack (KCNT1) are associated with terrible epilepsy syndromes that already begin in infancy." (PMID 37821582, 2023). "The heterozygous variant was identified in siblings affected with epilepsy syndromes and co-morbidities previously associated with mutation of KCNT1." (PMID 36499459, 2022).
Cognitive impairment (4 papers, 2015 to 2025). Abnormal cognition is characterized by deficits in thinking, reasoning, or remembering. "Alterations in KCNT1 or Slack channels disrupt the excitatory-inhibitory balance, contributing to cognitive deficits and neurological or psychiatric disorders." (PMID 41189825, 2025). "Eligible studies included those investigating potassium channels, with a particular focus on KCNT1/Slo2 channels in the context of ID or cognitive impairment." (PMID 41189825, 2025).
infantile spasms (4 papers, 2014 to 2021). A rare epilepsy syndrome characterized by onset of epileptic spasms in infants between 2 and 12 months of age, and rarely up to 24 months. "In our study, one KCNT1 (c.862G > A, p.G288S) mutation was found in a patient diagnosed as West syndrome." (PMID 30185235, 2018). "This is also the first reported case of paternal isodisomy for chromosome 9, and of an apparently recessive mutation in KCNT1; recently reported mutations causing MMPSI, ADNFLE and infantile spasms were all dominant." (PMID 24463883, 2014).
Anxiety (3 papers, 2020 to 2025). Intense feelings of nervousness, tension, or panic often arise in response to interpersonal stresses. "In models with complete Kcnt1 knockout, mice exhibited abnormal motor skill learning, altered open-field behavior, and anxiety-like traits, although spatial learning remained unaffected." (PMID 41189825, 2025). "In an open field test, which tests a variety of functions related to exploratory behavior including locomotor activity and anxiety, Kcnt1−/− mice had overall decreased movement (p = 0.016, N = 22, repeated measures ANOVA)." (PMID 32081855, 2020). "Survival, seizure frequency, and behavioral markers (nesting, exploratory, anxiety like [light/dark box test and EPM]) were examined to determine the efficacy of Kcnt1 knockdown." (PMID 36173683, 2022).
channelopathies (3 papers, 2020 to 2025). "Among the ion channel genes that could be targeted to treat channelopathies, KCNT1 is an attractive choice because reduced expression is well tolerated." (PMID 37901435, 2023).
Dravet syndrome (3 papers, 2020 to 2025). "Ion channelopathies like α1-sodium channel subunit (SCN1A) and sodium-activated potassium channel gene (KCNT1), typically associated with Dravet syndrome and sleep-related hypermotor epilepsy, respectively, can co-occur with histologically proven FCD." (PMID 33551717, 2020). "Eight individuals (6.2%) had died after their last follow-up; four had SCN1A-related Dravet syndrome; the others had CHD2, GNAO1, KCNT1 and NEXMIF-related DEEs." (PMID 39882024, 2025). "We also tested the effect of the Kcnt1 ASO in Scn1a+/− mice, a model of Dravet Syndrome." (PMID 37901435, 2023).
Encephalopathy (3 papers, 2021 to 2023). Encephalopathy is a term that means brain disease, damage, or malfunction. "Failures of precision therapies should be not underestimated, e.g., quinidine (and its derivatives) in KCNT1-activating mutations or phenytoin in patients with GoF SCN8A mutations and encephalopathy." (PMID 38003469, 2023).
periventricular nodular heterotopia (2 papers, 2022 to 2023). Periventricular nodular heterotopia (PNH) is a brain malformation, due to abnormal neuronal migration, in which a subset of neurons fails to migrate into the developing cerebral cortex and remains as nodules that line the ventricular surface. "Periventricular nodular heterotopia was observed in some patients with sleep-related hypermotor epilepsy and point mutations in the sodium-activated K+ channel KCNT1 (Slack or KNa1.1)." (PMID 35237124, 2022).
atherosclerosis (1 paper, 2022). A disease characterized by the build-up of fatty material and calcium deposition in the arterial wall resulting in partial or complete occlusion of the arterial lumen. "Top DMPs were annotated to the PTPRN2, SKIL, and KCNT1 genes, which have been reported in relation to cardiometabolic risk factors, atherosclerosis, and sodium-potassium handling." (PMID 36457109, 2022).
childhood epilepsy syndromes (1 paper, 2024). "More than a decade ago, autosomal dominant mutations were identified in the sodium-gated potassium channel KCNT1 in multiple patients with severe, childhood epilepsy syndromes." (PMID 39392867, 2024).
early-onset epilepsy (1 paper, 2018). "We report a cohort of patients with early-onset epilepsy associated with pathogenic variants in KCNT1, which encodes the sodium-activated potassium channel KCa4.1 (sequence like a calcium-dependent potassium channel [SLACK], Slo2.2)." (PMID 29196579, 2018).
Epileptic spasm (1 paper, 2022). A sudden flexion, extension, or mixed extension-flexion of predominantly proximal and truncal muscles that is usually more sustained than a myoclonic movement but not as sustained as a tonic seizure. "In this series, 8/36 patients (22.2%) had epileptic spasms, including those with KCNT1, SCN2A, SCN1A, DOCK6 and PCDH19 variants." (PMID 35715422, 2022).
glioma (1 paper, 2023). A benign or malignant brain and spinal cord tumor that arises from glial cells (astrocytes, oligodendrocytes, ependymal cells). "It should also be noted that the function of KCNC1, KCNT1, RIMS2, NECAP2, GNG5, SCAMP2, GNAI3 genes is also correlated with membrane function in low-grade gliomas." (PMID 37239411, 2023).
Hydrocephalus (1 paper, 2025). Hydrocephalus is an active distension of the ventricular system of the brain resulting from inadequate passage of CSF from its point of production within the cerebral ventricles to its point of absorption into the systemic circulation. "For example, ICV delivery of an antisense oligonucleotide (ASO) targeting a KCNT1 mutation induced severe, progressive hydrocephalus with fatal outcomes in a pediatric cohort." (PMID 41509429, 2025).
Lennox-Gastaut syndrome (1 paper, 2019). Lennox-Gastaut syndrome (LGS) belongs to the group of severe childhood epileptic encephalopathies. "In conclusion, quinidine therapy may offer a new choice for the treatment of Lennox-Gastaut syndrome with KCNT1 mutations." (PMID 30804880, 2019).
lung carcinoma (1 paper, 2022). "Following adjustment for CSI, the most frequently selected CpG site was KCNT1-cg00108873 which was hypomethylated in lung cancer cases." (PMID 35595947, 2022). "It has, to our knowledge never been associated to lung cancer risk, although recent work on gene expression identified low expression of KCNT1 consistently in four cancers, including lung." (PMID 35595947, 2022).
Obesity (1 paper, 2017). Accumulation of substantial excess body fat. "Even though no sufficient studies showed the association of two genes of KCNT1 and LBX1 with obesity, the results of functional annotation and enrichment analysis indicated that they were involved in intermediate-density lipoprotein particle and voltage-gated potassium channel complex, respectively." (PMID 29132311, 2017).
osteoarthritis (1 paper, 2025). A noninflammatory degenerative joint disease occurring chiefly in older persons, characterized by degeneration of the articular cartilage, hypertrophy of bone at the margins and changes in the synovial membrane. "In a clinical study with patients with osteoarthritis, mean circulating plasma levels of 0.3 μM antrafenine were measured, which is in the concentration range of the KCNT1 channel inhibition reported here." (PMID 40944494, 2025).
Pain (1 paper, 2021). An unpleasant sensory and emotional experience associated with actual or potential tissue damage, or described in terms of such damage. "Among the potential targets for treatment of neuropathic pain, the sodium (Na+)-dependent potassium (K+) channel Slack (also termed KNa1.1, Slo2.2, or Kcnt1) has gained recent interest." (PMID 33401689, 2021).
status epilepticus (1 paper, 2021). Status epilepticus is defined as a continuous seizure lasting more than 30 min, or two or more seizures without full recovery of consciousness between any of them. "Another patient with a KCNT1 mutation was affected by refractory status epilepticus, and seizures decreased with intravenous levetiracetam." (PMID 33827647, 2021).
movement disorder (3 papers, 2018 to 2024). Neurological conditions resulting in abnormal voluntary or involuntary movement, which may impact the speed, fluency, quality and ease of movement. "However, 5 of 12 pathogenic variant–positive patients with EIFMS presented with a severe movement disorder compared to 2 of 19 KCNT1-negative cases." (PMID 29196579, 2018).
neurodevelopmental disorder (2 papers, 2024 to 2025). A behavioral and cognitive disorder with onset during the developmental period that involves impaired or aberrant development of intellectual, motor, or social functions. "Taken together, these findings illustrate the importance of interrogating not only multiple neuron types but also multiple brain regions to fully unravel the complexity underlying KCNT1 GOF-related neurodevelopmental disorders." (PMID 39392867, 2024). "Thus, there is a critical need for a better understanding of how heterozygous expression of these KCNT1 variants in the developing brain alters neuronal physiology and network behavior to lead to such devastating neurodevelopmental disorders." (PMID 39392867, 2024). "This table presents details of experimental and review studies investigating Slo2 channels and KCNT1/KCNT2-related neurodevelopmental disorders." (PMID 41189825, 2025).
neurological disorder (2 papers, 2022 to 2025). "We analysed the properties of KCNT1 potassium currents and attempted to find a correlation between the changes in KCNT1 characteristics due to the mutations and severity of the neurological disorder they cause." (PMID 36499459, 2022). "We observed a positive correlation between the severity of the neurological disorder and the KCNT1 channel open probability at resting membrane potential." (PMID 36499459, 2022). "Search terms combined keywords and Medical Subject Headings (MeSH) relevant to Slo2 channels, KCNT1/KCNT2, sodium-activated potassium channels, ID, and neurological disorders." (PMID 41189825, 2025).
KCNT1 also shares sentences with these, for which no sentence is quoted: Angelman syndrome (3 papers); Ohtahara syndrome (3); cancer (2); early onset epileptic encephalopathy (2); Onset (2); sleep-related hypermotor epilepsy (2); autism (1); behavior disorders (1); breast carcinoma (1); cardiac hypertrophy (1); Coffin-Siris syndrome (1); convergent strabismus (1); cryptorchidism (1); encephalomalacia (1); fragile X syndrome (1); fructose intolerance (1); genetic disorder (1); Hypertension (1); Hypsarrhythmia (1); infantile epileptic encephalopathy (1); leukodystrophy (1); Leukoencephalopathy (1); migraine (1); molybdenum cofactor deficiency type A (1); Nystagmus (1); osteosarcoma (1); Pachygyria (1); Parasomnia (1); polymicrogyria (1); Rett syndrome (1).
A further 5 diseases each share a sentence with KCNT1 in 1 paper.